NUDT7 (nudix hydrolase 7)
Description:
Fatty acyl-coenzyme A (CoA) diphosphatase that hydrolyzes fatty acyl-CoA to yield acyl-4'-phosphopantetheine and adenosine 3',5'-bisphosphate (By similarity). Cleaves CoA, CoA esters and oxidized CoA with similar efficiencies (By similarity). Preferentially hydrolyzes medium-chain acyl-CoAs and bile acid-CoAs (By similarity). Has no activity toward NDP-sugars, CDP-alcohols, (deoxy)nucleoside 5'-triphosphates, nucleoside 5'-di or monophosphates, diadenosine polyphosphates, NAD, NADH, NADP, NADPH or thymidine-5'-monophospho-p-nitrophenyl ester (By similarity). May be required to eliminate oxidized CoA from peroxisomes, or regulate CoA and acyl-CoA levels in this organelle in response to metabolic demand (By similarity). Does not play a role in U8 snoRNA decapping activity (By similarity). Binds U8 snoRNA (By similarity). Exhibits decapping activity towards dpCoA-capped RNAs in vitro (By similarity).
Tractability: Small molecule: a structure with a bound ligand is known. PROTAC: ubiquitination databases record sites on it.
Gene: Protein-coding gene on chromosome 16 (77,722,485 to 77,742,260, forward strand). Ensembl gene ENSG00000140876.
Subcellular location: Peroxisome
Subcellular location (Human Protein Atlas): Golgi apparatus; Nucleoplasm
Pathways (Reactome):
Metabolism: Peroxisomal lipid metabolism
Protein localization: Peroxisomal protein import
Gene Ontology:
Molecular function: 5'-(N(7)-methylguanosine 5'-triphospho)-[mRNA] hydrolase activity; coenzyme A diphosphatase activity; magnesium ion binding; snoRNA binding; hydrolase activity, acting on acid anhydrides, in phosphorus-containing anhydrides; manganese ion binding
Biological process: acetyl-CoA catabolic process; butyryl-CoA catabolic process; coenzyme A catabolic process; malonyl-CoA catabolic process; medium-chain fatty-acyl-CoA catabolic process; propionyl-CoA catabolic process; propionyl-CoA metabolic process; succinyl-CoA catabolic process
Cellular component: cytosol; peroxisomal matrix; peroxisome
Genetic constraint (gnomAD): Loss-of-function variants: 20 observed, 12.51 expected, observed/expected ratio (o/e) 1.6, 90% interval 1.1 to 1.94. The upper end of that interval is the gene's LOEUF score, 1.94, which puts it in group 6 of 6, group 1 being the genes least tolerant of losing a copy. Missense variants: 360 observed, 303.26 expected, observed/expected ratio (o/e) 1.19, 90% interval 1.09 to 1.29. Synonymous variants: 132 observed, 114.22 expected, observed/expected ratio (o/e) 1.16, 90% interval 1 to 1.34.
Homologues: Orthologues: chimpanzee NUDT7 (99% identical), macaque NUDT7 (96% identical), dog NUDT7 (72% identical), pig NUDT7 (70% identical), guinea pig NUDT7 (68% identical), mouse Nudt7 (64% identical), rabbit NUDT7 (64% identical), rat Nudt7 (63% identical), tropical clawed frog nudt7 (44% identical), zebrafish nudt7 (37% identical).
Diseases named in the same sentence as NUDT7 in open-access papers:
NUDT7 is named in the same sentence as 18 diseases in open-access papers, as found by Europe PMC text mining. Sharing a sentence is not in itself a finding about the gene and the disease. The quoted sentences say what the papers report.
glioma (2 papers, 2022). A benign or malignant brain and spinal cord tumor that arises from glial cells (astrocytes, oligodendrocytes, ependymal cells). "After performing Cox univariate and LASSO Cox regression analyses, we selected three genes (NUDT7, NUDT11, and CYFIP2) to construct a risk score model that stratified glioma patients into low- and high-risk groups." (PMID 35614925, 2022). "In this study, we demonstrate for the first time that the risk scores of NUDT7, NUDT11, and CYFIP2 can be used as independent prognostic factors for gliomas." (PMID 35614925, 2022). "The results showed that NUDT7, NUDT11, and CYFIP2 were all protective factors for OS in glioma patients." (PMID 35614925, 2022). "Recently, the effect of m7G RNA methylation regulators on glioma prognosis has been investigated, where three genes (NUDT7, NUDT11 and CYFIP2) have been proposed as promising prognostic biomarkers for gliomas." (PMID 36012529, 2022). "The univariate Cox regression analysis of these genes showed that NUDT7, NUDT11, and CYFIP2 are all protective factors with a hazard ratio (HR) of less than 1 for the OS of glioma patients." (PMID 35614925, 2022).
adenoma (1 paper, 2020). A neoplasm arising from the epithelium. "Restoration of Nudt7 by tail-vein injection into Nudt7−/− mice significantly reduced the development of adenoma observed in Nudt7−/− mice colons and the number of FABP4-, FASN-, Ki67-, CD45-, and SCD1-positive cells." (PMID 32131398, 2020). "Analysis of GSE8671 (comparison between 32 prospectively collected adenomas and normal mucosa from the same individuals) also showed a significant decrease in Nudt7 in CRC." (PMID 32131398, 2020).
adenomatous colonic polyps (1 paper, 2020). "We observed the increase in infiltration of inflammatory cells, a key feature of sporadic adenomatous colonic polyps with an increased number of Ki67-, CD45-, β-catenin-, proliferating cell nuclear antigen (PCNA)-, and F4/80-positive cells in the Chi/PA-attached Nudt7+/+ colon polyp." (PMID 32131398, 2020).
clear cell renal cell carcinomas (1 paper, 2022). "In clear cell renal cell carcinomas the alternative splicing of NUDT7 was found to be correlated with overall survival time." (PMID 36298586, 2022).
colorectal cancer (1 paper, 2022). A primary or metastatic malignant neoplasm that affects the colon or rectum. "Mutations of NUDT7 have been described in colorectal cancer, inhibition of Nudt7 may contribute to the progression of Kras G12D colorectal cancer through upregulation of Wnt/β-catenin signaling and palmitic acid accumulation." (PMID 35614925, 2022).
esophageal adenocarcinoma (1 paper, 2022). A malignant tumor with glandular differentiation arising predominantly from Barrett mucosa in the lower third of the esophagus. "Similarly, the increased expression of HSPH1, IDH3G, NUDT7 and PDHA1 was associated with shorter OS in the subgroup of patients suffering from esophageal adenocarcinoma (EAD)." (PMID 36298586, 2022).
Hepatic steatosis (1 paper, 2023). Steatosis is a term used to denote lipid accumulation within hepatocytes. "Knockout of Acaa1a, Nudt7 or Pex11ɑ promoted hepatic steatosis 30-33." (PMID 37063432, 2023).
polyp (1 paper, 2020). A usually exophytic mass attached to the underlying tissue by a broad base or a thin stalk. "To identify the role of Nudt7 in the development of CRC, we induced colonic polyp formation using an azoxymethane/dextran sulfate sodium (AOM/DSS) method using Nudt7 knock-out (KO, Nudt7−/−) mice." (PMID 32131398, 2020).
viral infection (1 paper, 2026). "We also found NUDT7 enhance PRRSV replication by reprograms viral infection-induced intracellular lipid droplets (LDs) synthesis." (PMID 41608635, 2026).
tumor (5 papers, 2020 to 2024). "Here, we found that downregulation of Nudt7 leads to VLCFA accumulation, and overexpression of Nudt7 inhibits in vitro proliferation and in vivo xenograft tumor growth of KrasG12D CRC cells." (PMID 32131398, 2020). "The subcutaneous mouse model of KrasG12D cells, LS-174T, showed that overexpression of Nudt7 significantly decreased tumor mass (3.36-fold of control (Con))." (PMID 32131398, 2020). "In this study, we evaluate the importance of peroxisomal function in KrasG12D CRC and identify peroxisomal coenzyme A diphosphatase NUDT7 (NUDT7) as a potent tumor suppressor to restrict KrasG12D CRC progression." (PMID 32131398, 2020). "On the other hand, NUDT7 expression was decreased by over two-fold in tumor cells." (PMID 39038933, 2024). "Since the important role of CoA homeostasis in tumor growth and malignant progression has been suggested, NUDT7 may play an important role in cancer development by altering CoA pools." (PMID 32131398, 2020). "Moreover, Nudt7−/− mice showed a significantly more pronounced increase in the expression levels of genes involved in the development of CRC, suggesting NUDT7 as a novel potent tumor suppressor for CRC." (PMID 32131398, 2020). "ADH5, NUDT7, PTGES3, D2HGDH, HAO2 and CPT1C also play regulatory roles in the pathological processes of various tumours." (PMID 36643625, 2023). "We found that the expression level of β-catenin was significantly increased both in Nudt7−/− mice colons treated with AOM/DSS and the patient colon of KrasG12D tumor." (PMID 32131398, 2020). "Analysis of fatty acid composition using clinical adjacent normal (non-tumor) and CRC tissues as well as Caco2 cells transfected with shCon or shNudt7 showed a significant increase in palmitic acid (PA), suggesting the possible involvement of Nudt7 in the accumulation of PA." (PMID 32131398, 2020).
cancer (4 papers, 2013 to 2022). A tumor composed of atypical neoplastic, often pleomorphic cells that invade other tissues. "Notably, the expression and potential role of NUDT7, NUDT11, and CYFIP2 in cancer are becoming increasingly important." (PMID 35614925, 2022). "However, the function of Nudt7 in cancer has not been well studied." (PMID 32131398, 2020).
infection (3 papers, 2016 to 2023). The state of being infected such as from the introduction of a foreign agent such as serum, vaccine, antigenic substance or organism. "Particularly, Arabidopsis NUDT7 and wheat TaNUDX23 have been identified to negatively regulate EDS1-dependent SA biosynthesis and ROS accumulation to facilitate pathogen infection." (PMID 37108797, 2023).
adenocarcinoma (2 papers, 2020 to 2022). A common cancer characterized by the presence of malignant glandular cells. "Additionally, Nudt7-/- mice treated with a combination of azoxymethane and dextran sulfate sodium develop more polyps and adenocarcinoma than WT mice." (PMID 36436558, 2022).
NUDT7 also shares sentences with these, for which no sentence is quoted: colon polyp (1 paper); Fanconi anemia (1); hypothyroidism (1); immune deficiency (1); osteoarthritis (1).